PSMB4 (proteasome 20S subunit beta 4)
Description:
Non-catalytic component of the 20S core proteasome complex involved in the proteolytic degradation of most intracellular proteins. This complex plays numerous essential roles within the cell by associating with different regulatory particles. Associated with two 19S regulatory particles, forms the 26S proteasome and thus participates in the ATP-dependent degradation of ubiquitinated proteins. The 26S proteasome plays a key role in the maintenance of protein homeostasis by removing misfolded or damaged proteins that could impair cellular functions, and by removing proteins whose functions are no longer required. Associated with the PA200 or PA28, the 20S proteasome mediates ubiquitin-independent protein degradation. This type of proteolysis is required in several pathways including spermatogenesis (20S-PA200 complex) or generation of a subset of MHC class I-presented antigenic peptides (20S-PA28 complex). SMAD1/OAZ1/PSMB4 complex mediates the degradation of the CREBBP/EP300 repressor SNIP1.
Synonyms: PROS-26; HsN3; PROS26; HN3; PRAAS3
Tractability: Small molecule: an approved drug acts on it; a structure with a bound ligand is known; a high-quality ligand is known; it belongs to a druggable protein family. PROTAC: ubiquitination databases record sites on it; its protein half-life has been measured; a small molecule that binds it is known.
Target class: Threonine protease; Protease; Threonine protease T1A subfamily; Threonine protease PBT clan; Enzyme
Gene: Protein-coding gene on chromosome 1 (151,399,556 to 151,401,941, forward strand). Ensembl gene ENSG00000159377.
Subcellular location: Cytoplasm; Nucleus
Subcellular location (Human Protein Atlas): Nucleoplasm; Mitochondria
Pathways (Reactome):
Immune System: AMPK-induced ERAD and lysosome mediated degradation of PD-L1(CD274); Activation of NF-kappaB in B cells; Antigen processing: Ub, ATP-independent proteasomal degradation; Antigen processing: Ubiquitination & Proteasome degradation; CLEC7A (Dectin-1) signaling; Cross-presentation of soluble exogenous antigens (endosomes); Dectin-1 mediated noncanonical NF-kB signaling; Downstream TCR signaling; ER-Phagosome pathway; FCERI mediated NF-kB activation; GSK3B-mediated proteasomal degradation of PD-L1(CD274); Interleukin-1 signaling; NIK-->noncanonical NF-kB signaling; SPOP-mediated proteasomal degradation of PD-L1(CD274); TNFR2 non-canonical NF-kB pathway
Cell Cycle: APC/C:Cdc20 mediated degradation of Securin; APC/C:Cdh1 mediated degradation of Cdc20 and other APC/C:Cdh1 targeted proteins in late mitosis/early G1; Autodegradation of Cdh1 by Cdh1:APC/C; Autodegradation of the E3 ubiquitin ligase COP1; Cdc20:Phospho-APC/C mediated degradation of Cyclin A; FBXL7 down-regulates AURKA during mitotic entry and in early mitosis; G2/M Checkpoints; SCF(Skp2)-mediated degradation of p27/p21; SCF-beta-TrCP mediated degradation of Emi1; Separation of Sister Chromatids; The role of GTSE1 in G2/M progression after G2 checkpoint; Ubiquitin-Mediated Degradation of Phosphorylated Cdc25A; Ubiquitin-dependent degradation of Cyclin D
Signal Transduction: Asymmetric localization of PCP proteins; Degradation of AXIN; Degradation of DVL; Degradation of GLI1 by the proteasome; Degradation of GLI2 by the proteasome; Degradation of beta-catenin by the destruction complex; GLI3 is processed to GLI3R by the proteasome; Hedgehog 'on' state; Hedgehog ligand biogenesis; MAPK6/MAPK4 signaling; Negative regulation of NOTCH4 signaling; Regulation of PTEN stability and activity
and 28 more pathways
Gene Ontology:
Molecular function: protein binding; structural constituent of proteasome; lipopolysaccharide binding
Biological process: proteasomal protein catabolic process; proteasome-mediated ubiquitin-dependent protein catabolic process; regulation of proteasomal protein catabolic process; response to oxidative stress; apoptotic process; CD8-positive, alpha-beta T cell differentiation; CD8-positive, alpha-beta T cell homeostasis; cellular response to type I interferon; DNA damage response; DNA repair; flagellated sperm motility; immune system process; meiotic cell cycle; negative regulation of regulatory T cell differentiation; positive regulation of interleukin-2 production; positive regulation of tumor necrosis factor production; positive regulation of type II interferon production; proteasomal ubiquitin-independent protein catabolic process; regulation of G1/S transition of mitotic cell cycle; response to type II interferon; spermatogenesis; T-helper 1 cell differentiation; T-helper 17 cell differentiation; thymic T cell selection; negative regulation of inflammatory response to antigenic stimulus; and 1 more
Cellular component: ciliary basal body; cytoplasm; extracellular exosome; nucleoplasm; nucleus; proteasome complex; proteasome core complex; cytosol; proteasome core complex, beta-subunit complex; proteasome storage granule; spermatoproteasome complex; synaptic vesicle
Genetic constraint (gnomAD): Loss-of-function variants: 16 observed, 36.88 expected, observed/expected ratio (o/e) 0.43, 90% interval 0.29 to 0.66. The upper end of that interval is the gene's LOEUF score, 0.66, which puts it in group 2 of 6, group 1 being the genes least tolerant of losing a copy. Missense variants: 332 observed, 374.17 expected, observed/expected ratio (o/e) 0.89, 90% interval 0.81 to 0.97. Synonymous variants: 144 observed, 144.23 expected, observed/expected ratio (o/e) 1, 90% interval 0.87 to 1.15.
Homologues: Orthologues: chimpanzee PSMB4 (99% identical), macaque PSMB4 (99% identical), rabbit PSMB4 (94% identical), pig PSMB4 (94% identical), mouse Psmb4 (94% identical), guinea pig PSMB4 (93% identical), rat Psmb4 (92% identical), zebrafish psmb4 (73% identical), tropical clawed frog psmb4 (73% identical), dog PSMB4 (72% identical), Drosophila melanogaster Prosbeta7 (38% identical), Caenorhabditis elegans pbs-7 (30% identical). Paralogues in human: PSMB6 (20% identical), PSMB8 (19% identical), PSMB11 (19% identical), PSMB5 (18% identical), PSMB7 (18% identical), PSMB9 (18% identical), PSMB10 (17% identical), PSMA8 (17% identical), PSMA7 (16% identical), PSMB1 (16% identical), PSMA4 (15% identical), PSMA1 (14% identical), and 6 more.